ALB (albumin)
Diseases named in the same sentence as ALB in open-access papers (continued):
Sharing a sentence is not in itself a finding about the gene and the disease.
sarcopenia (continued). "Sarcopenia is considered to be a better predictive tool than BMI and albumin for survival." (PMID 35177018, 2022). "Multivariate analysis was performed on the following eight factors selected using stepwise logistic regression of factors significantly associated with sarcopenia in univariate analysis: age, low BMI, PDFF, ALT, albumin, total cholesterol, prothrombin activity, and HCC." (PMID 35542962, 2022). "Men with sarcopenia had lower levels of red blood cells, hemoglobin, and albumin." (PMID 35337292, 2022). "The prevalence of sarcopenia was 19.5%, and it was higher in patients with a longer hospital stay and lower in patients who were more physically active and had higher levels of serum albumin." (PMID 35698920, 2022). "On univariate analysis, independent survival predictors were the presence of pre-SBRT sarcopenia, SMI loss, biological effective dose, ECOG, presence of extrahepatic metastasis, neutrophil-to-lymphocyte ratio (NLR), albumin-bilirubin score, tumor size, multiple tumors, and macrovascular invasion." (PMID 36352042, 2022). "In addition, the level of serum albumin was related to the sarcopenia determined by each calculation method." (PMID 35655215, 2022). "In the present study, we tried to determine if coenzyme Q10 and the skeletal muscle protein biomarkers such as albumin, creatine kinase, irisin, and myostatin, could be used to assist in the diagnosis of sarcopenia." (PMID 35453410, 2022). "In other words, although accurate preoperative clinical selection was performed in all patients, indeed the preoperative albumin levels were normal in 96.7% of patients, and only 4 patients (13.3%) presented underweight, the incidence of sarcopenia was high (50.0%)." (PMID 35329856, 2022). "Along with the PMV, BMI (0.164), bilirubin (0.158), preoperative Hb (0.132), albumin (0.131), total protein (0.123) and age (0.113) were key features for sarcopenia prediction; PMV, BMI, Hb, total protein and age also showed statistical significance (p < 0.05) in a univariate analysis." (PMID 35806895, 2022). "A multi-center study conducted in the USA showed that sarcopenia is more prevalent in patients with inflammatory bowel disease undergoing surgery, while the clinical nutrition markers including the body mass index and albumin were similar in the population." (PMID 36684140, 2022). "Biomarkers associated with nutrition (including albumin, vitamin D, and IGF-1) can be used to evaluate nutritional status and muscle mass, strength, and function in individuals, aiding in the identification and treatment of sarcopenia." (PMID 35892736, 2022). "The serum albumin level also gradually decreased in the sarcopenia group (P < 0.001)." (PMID 36444383, 2022). "However, we still recommend that it is necessary to monitor the albumin status as aging progresses and sarcopenia progresses." (PMID 35453410, 2022). "In conclusion, sarcopenia and other indexes of body composition such as lower serum albumin may be valuable to identify potential nutritional problems and poorer survival in our study." (PMID 35501704, 2022). "Multivariate analysis revealed that serum albumin [HR 0.658 (0.470–0.923); p = 0.023], sarcopenia [HR 1.638 (1.113–2.410); p = 0.016], TNM stage [HR 2.439 (1.710–3.228); p < 0.0001], and N stage [HR 0.483 (0.262–0.890); p < 0.0001] were independent prognostic factors for OS in ESCC patients." (PMID 35501704, 2022). "In this study, we found that sarcopenia was associated with low height-for-age, low BMI-for-age, high levels of inflammatory markers such as CRP and ESR, and low levels of hemoglobin, hematocrit, and albumin in 105 children diagnosed with primary CD." (PMID 35608430, 2022). "PNI, sarcopenia, BMI and serum albumin levels reflect nutritional status." (PMID 34067286, 2021). "AWGS2 and IWGS provided independent correlations between serum albumin level and sarcopenia." (PMID 34943268, 2021).
sarcopenia (continued). "We conducted a multicenter clinical study to construct a novel index based on a combination of albumin-globulin score and sarcopenia (CAS) that can comprehensively reflect patients' nutritional and inflammatory status and assess the prognostic value of CAS in renal cell carcinoma (RCC) patients." (PMID 34631767, 2021). "Compared with the low PA group, the OR of moderate to high PA to sarcopenia was 0.46 (95% CI 0.27–0.79, p-value = 0.005) after adjusting for sex, institutionalization, age, BMI, albumin, hemoglobin, HDL-C levels, history of cardiovascular disease, education level and alcohol drinking." (PMID 34075104, 2021). "In the univariate analysis, low BMI (P = 0.049), low HBI (P = 0.027), low preoperative levels of serum albumin (P = 0.001), low prealbumin levels (P = 0.009), emergency surgery (P = 0.002), and colostomy and sarcopenia (P = 0.026) were identified as factors related to postoperative complications." (PMID 34608386, 2021). "At present, a variety of predictors have been proposed to predict outcomes after surgery, such as the C-reactive protein (CRP), procalcitonin (PCT), platelet-to-lymphocyte ratio (PLR), neutrophil to lymphocyte ratio (NLR), body mass index (BMI), sarcopenia, and albumin (ALB) levels." (PMID 33727917, 2021). "Moreover, weight loss ≥ 5% in the previous 6 months (46.8% versus 22.2%, p = 0.001) and serum albumin < 35 g/L (23.4% vs 11.1%, p = 0.033) were more frequently observed in the sarcopenic patients than in non-sarcopenia patients." (PMID 34307131, 2021). "According to previously reported data, the factors associated with ambulation capacity after hip fracture include age, gender, prefracture ambulatory capacity and combined medical disease, cognitive status, serum albumin, serum folic acid, visual impairment, sarcopenia, and impaired communication." (PMID 33482788, 2021). "Low serum albumin levels have also been reported to be low in those with sarcopenia." (PMID 34205795, 2021). "In addition, the group with a low preOP serum albumin level (≤3.5 g/dL) had a lower risk of SKM mass reduction during survival, which can be interpreted as the same mechanism as preOP sarcopenia." (PMID 34362219, 2021). "In recent years, the role of inflammation or nutrition-related factors, including NLR, PLR, albumin levels, and sarcopenia, in malignant tumors have attracted increased attention as significant predictors for various cancers that can reflect tumor' progression 7, 8, 14-16." (PMID 32913461, 2020). "Since the association between preoperative metabolic reserve, manifested among others by sarcopenia and decreased albumin levels, and heavily influenced by age and disease burden is well known by the common surgeon, one can contemplate why patients in this condition were selected for surgery." (PMID 32238149, 2020). "Sarcopenia was significantly associated with urinary albumin level regardless of age, the procedures of sarcopenia assessment, eGFR, and sex." (PMID 31828155, 2019). "Our finding, which showed sarcopenia at a lower serum albumin and total protein level, may be attributed to protein energy malnutrition, consistent with previous studies." (PMID 31681607, 2019). "In multivariate analysis [reporting hazard ratio (HR): 95% confidence interval (CI)], albumin-bilirubin score (2.35: 1.33–4.17; p = 0.003), total dose (0.44: 0.27–0.71; p = 0.001), and pre-RT sarcopenia (2.38: 1.53–3.70; p < 0.001) were independent OS prognostic factors." (PMID 31681607, 2019). "In addition to age, duration of HD, BMI, and serum albumin levels, the presence of DM was determined to be an independent contributor to sarcopenia in patients undergoing HD (OR 3.11; 95% CI 1.63–5.93; p < 0.001)." (PMID 30922266, 2019). "BMI, OR 0.8, 95% CI [0.7, 0.9] and serum albumin, OR 0.9 95% CI [0.8, 1.0], were associated with not having sarcopenia." (PMID 28902873, 2017).
sarcopenia (continued). "Univariate binomial logistic regression analyses revealed that age (positively), female gender (positively), adiponectin (positively), sialic acid (positively), BMI (inversely), albumin (inversely), and eGFR (inversely) significantly correlated with sarcopenia." (PMID 28542531, 2017). "Sarcopenia was associated with lower BMI (P <0.001), poorer PS (P = 0.001), higher ALP (P = 0.002), higher Bajorin’s score (P = 0.003), advanced age (P = 0.016), visceral metastasis (P = 0.017), and lower albumin (P = 0.018)." (PMID 25612215, 2015). "This may reflect how poorly BMI and albumin levels detect potential sarcopenia in these patients." (PMID 40630784, 2025). "Moreover, in sarcopenia group, Hb and ALB were lower (80.8 ± 22 vs. 88.1 ± 25 g L−1, p = 0.007; 33.5 ± 12.5 vs. 36.6 ± 13.5 g L−1, p = 0.020), and both LE8 and LC9 scores were markedly reduced (LE8: 63.3 ± 12.3 vs. 67.6 ± 10.3, p = 0.001; LC9: 60.4 ± 11.6 vs. 68.4 ± 10.8, p < 0.001)." (PMID 41404588, 2025). "However, the direct relationship between sarcopenia and blood albumin levels remains unconfirmed." (PMID 40538582, 2025). "We determined sarcopenia risk (SARC-F tool), FRAIL scale, handgrip strength, calf circumference (CC), body mass index (BMI), Charlson index (CI), nutritional status (MNA-SF), serum albumin, dependency degree (Barthel index), and quality of life with EQ5D5L questionnaire." (PMID 40971021, 2025). "Furthermore, patients with sarcopenia exhibited a greater prevalence of nutritional risk (NRS ≥ 3) and COPD, alongside lower serum albumin levels, higher total bilirubin, elevated serum creatinine, reduced triglycerides, increased C-reactive protein, and lower eGFR (all p values < 0.05)." (PMID 41262732, 2025). "In addition, the NNRD group also increased their plasma albumin compared with the control group, indicating sufficient protein intake and thus not an association with the risk of sarcopenia." (PMID 38999786, 2024). "This may also explain the negative association between serum albumin, a marker of inflammation, and frailty and sarcopenia, regardless of participant age and setting." (PMID 38792928, 2024). "Thus, sarcopenia may have a better prognostic value when combined with the C-reactive protein-to-albumin ratio." (PMID 38913646, 2024). "Older age; lower BMI, albumin, prealbumin, predialysis BUN, predialysis creatinine, and phosphorus levels; lower CSA of the thigh muscle, L3 trunk muscle, G. Med/MinM, and G. MaxM; and a higher PDFF of the thigh and L3 trunk muscle were identified as sarcopenia risk factors." (PMID 37033264, 2023). "Thus, the pretreatment assessment of sarcopenia and measurement of albumin levels may be of great help in predicting prognosis after surgical treatment for patients with nonmetastatic RCC." (PMID 37371699, 2023). "There may have been some influencing factors that were left out of the research, such as baseline characteristics (albumin, sarcopenia, BMI, patient income, medical costs, and health insurance), as well as other factors that may have had an effect on the outcomes." (PMID 37777739, 2023). "Interestingly, among nutritional parameters, sarcopenia was associated with prealbumin rather than albumin, suggesting a somewhat acute process." (PMID 37058153, 2023). "A recent meta-analysis of 80 studies involving 33,160 older individuals aged 60–88 years found shared biomarkers between frailty and sarcopenia, including albumin and hemoglobin, which could one day allow for monitoring of the frailty phenotype and aid in clinical decision-making." (PMID 37891864, 2023). "Serum albumin levels did not have a significant association with sarcopenia." (PMID 37685565, 2023). "We found an association between low albumin value and mortality in patients without sarcopenia." (PMID 37770828, 2023). "In addition, plasma albumin levels are significantly reduced in patients with sarcopenia." (PMID 36191303, 2022).
sarcopenia (continued). "Hence, further studies are needed to determine whether urinary albumin, like urinary L-FABP, is a risk factor for the onset of sarcopenia." (PMID 32405506, 2020). "To conclude, sarcopenia assessed by CT sequence on PET-CT at baseline is an independent and robust prognostic factor of overall survival in patients with LAOC treated exclusively by radiochemotherapy, more prognostic than WHO score, BMI, albumin levels and weight loss." (PMID 32443967, 2020). "Subsequently, multivariate Cox proportional hazards analyses were performed to confirm whether age, duration of HD, gender, BMI, presence of DM, serum albumin levels, presence of sarcopenia, Kt/V, and nPCR were independent predictors of mortality in patients with HD." (PMID 30922266, 2019). "To date, TNF-α, IL-6, albumin and CRP have shown a relation with the development of low muscle strength or muscle mass over time, however, the current body of evidence fails to reveal a marker of chronic inflammation that is univocally associated with measures of sarcopenia in older people." (PMID 31455238, 2019). "Albumin as nutrition measure could be connected with low body mass index (BMI) and sarcopenia." (PMID 30302342, 2018). "The Spearman correlation and binary logistic regression analyses revealed the potential associations between depression and several factors, such as age, albumin, C-reactive protein, GNRI, and sarcopenia score (p < 0.05)." (PMID 41788681, 2026). "Our results indicate that the albumin-bilirubin (ALBI) score is particularly significant for sarcopenia, ranking higher than conventional biomarkers such as alanine aminotransferase (ALT), aspartate aminotransferase (AST), albumin, and bilirubin." (PMID 40686817, 2025). "Our findings suggest that sarcopenia may be a relevant prognostic indicator of medium-term mortality in this population, even after adjusting for other clinical variables such as the Charlson comorbidity index, the body mass index, and albumin and procalcitonin levels." (PMID 40725756, 2025). "The circulating factors in sarcopenia group were significantly lower: ALT, AST, ALB, γ-GT, CREA, UA, GLU, TG, LDL, GDF15, TNF-α and IL6." (PMID 40969368, 2025). "BMI, serum ALB, FGF19, and TNF-α levels were lower in the older adults population with sarcopenia, while GDF11 was higher in the serum of patients with sarcopenia." (PMID 40969368, 2025). "For PFS, ECOG performance status, albumin levels, BMI, SFI, sarcopenia, PNI, and CAR demonstrated significant correlations (P < 0.05)." (PMID 40667434, 2025). "Additionally, patients with impaired liver function often experience chronic inflammation and metabolic disturbances, which not only affect the metabolism of albumin and bilirubin but may also promote muscle breakdown, further exacerbating the development of sarcopenia or myosteatosis." (PMID 40308633, 2025). "In the comparison of laboratory indexes, we found that SFTS patients with sarcopenia had lower PLT and albumin, and higher PCT, BUN, and CREA." (PMID 40988472, 2025). "Multivariate analysis showed that sarcopenia (Hazard Ratio HR 2.84, 95%CI [1.45–5.57], p = 0.002), KPS score, albumin level and N stage were independent prognostic factors for OS." (PMID 40051963, 2025). "We then performed a multivariate analysis including sarcopenia plus LMR status, T classification, and albumin which showed significant differences in univariate analysis." (PMID 38549928, 2024). "In univariate analysis, age, sex, BMI, diagnosis, donor type, conditioning regimen, stem cell source, albumin, total protein, baseline SFI, baseline sarcopenia, ΔPMI1, ΔPMI3, ΔPMI6, and ΔPMI12 were included as candidate variables in the multivariate model." (PMID 38526005, 2024). "Despite having a higher BMI (p = 0.006), they exhibited lower albumin and prealbumin levels (p = 0.001; p = 0.01) and had worse scores for predicting PEW and sarcopenia (SARC-F: p = 0.008; MIS: p = 0.01)." (PMID 39337040, 2024).
sarcopenia (continued). "In NHANES, compared with non-MHF with MD, MHF was related to higher risks of advanced fibrosis (P = .036), elevated albumin–creatinine ratio (UACR, P = .001), and sarcopenia (P = .013)." (PMID 38124275, 2024). "Moreover, muscle function assessment (i.e. handgrip strength) to assess sarcopenia was not performed, as well as the measurements of several biochemical parameters that correlate with frailty, in particular albumin, whose association with ERCP-outcomes is still little investigated." (PMID 39859962, 2024). "The OFI-8 score was significantly associated with older age, the presence of osteoporosis, lower serum creatinine, albumin, and total cholesterol levels, lower GNRI and MNA-SF scores, higher NRI-JH and revised J-CHS scores, and the severity of sarcopenia." (PMID 39458463, 2024). "Regarding the biochemical parameters, the sarcopenia group had higher CRP levels (P <0.001) and lower serum phosphorus (P =0.033), serum magnesium (P=0.004), and albumin (P=0.002) levels." (PMID 37265691, 2023). "Univariate Cox regression analysis revealed that BMI, sarcopenia, KPS score, hCRP level, and albumin level were significant prognostic factors for PFS (all p < 0.05)." (PMID 36969820, 2023). "Blood measurements and the use of glucose-lowering drugs were comparable, except that albumin and LDL-cholesterol were lower in the sarcopenia+ group." (PMID 36819693, 2023). "Applying the status of weight in the formula, GNRI can be a better predictor than serum albumin for low SMI and sarcopenia in the elderly with T2DM with a median age of 80 [IQR 74, 86]." (PMID 36819693, 2023). "Participants with sarcopenia had lower L3-SMI, L3-SMA, gait speed, total cholesterol, albumin, weight, BMI, and mid-arm muscle circumference than those without comorbidities (p < 0.001)." (PMID 38071233, 2023). "The serum level of albumin was significantly decreased, (P = .047), and high-sensitivity C-reactive protein level (CRP) was significantly increased (P = .003) in sarcopenia group." (PMID 37960747, 2023). "Additionally, albumin was significantly associated with the presence or absence of sarcopenia." (PMID 37906352, 2023). "Clinical cutoffs of albumin (ALB), globulin (GLB), and sarcopenia were defined by receiver operating curve (ROC)." (PMID 36983238, 2023). "Third, this was a cross-sectional observational study, and low albumin followed by lower GNRI and the prevalence of low SMI and sarcopenia are mutually well-correlated." (PMID 36819693, 2023). "In the entire patient cohort, univariate Cox regression analysis revealed that BMI, sarcopenia, KPS score, levels of hemoglobin, hypersensitive C-reactive protein (hCRP) and albumin were significant prognostic factors for OS (all p < 0.05)." (PMID 36969820, 2023). "For the first time, we demonstrated a significantly higher CRP/albumin ratio and an elevated level of cfDNA in the group with diagnosed sarcopenia compared to the older adult without sarcopenia, thereby indicating that the two parameters could be used as novel biomarkers of sarcopenia." (PMID 37465171, 2023). "Although reduced hand-grip strength and sarcopenia were less common, the muscle quality, or phase angle (BIA), decreased during follow-up, also correlating with serum albumin and muscle mass (p ≤ 0.01)." (PMID 36678209, 2023). "This might explain the negative association of albumin with frailty and sarcopenia." (PMID 37762867, 2023). "The baseline characteristics of the CT-H and H-CT groups were similar in sex, age, tumor sidedness, serum albumin and serum CEA, except for sarcopenia." (PMID 37106073, 2023). "The area under ROC curve for NLR of MHD patients with sarcopenia was 0.695, and NLR was negatively correlated with a biochemical indicator—human blood albumin (P < 0.05)." (PMID 36895911, 2023). "Second, the superiority of GNRI as compared to albumin and CONUT for sarcopenia was also observed in the subclasses." (PMID 36819693, 2023).